DIAPH1 (diaphanous related formin 1)
Description:
Actin nucleation and elongation factor required for the assembly of F-actin structures, such as actin cables and stress fibers (By similarity). Binds to the barbed end of the actin filament and slows down actin polymerization and depolymerization (By similarity). Required for cytokinesis, and transcriptional activation of the serum response factor (By similarity). DFR proteins couple Rho and Src tyrosine kinase during signaling and the regulation of actin dynamics (By similarity). Functions as a scaffold protein for MAPRE1 and APC to stabilize microtubules and promote cell migration (By similarity). Has neurite outgrowth promoting activity. Acts in a Rho-dependent manner to recruit PFY1 to the membrane (By similarity). In hear cells, it may play a role in the regulation of actin polymerization in hair cells. The MEMO1-RHOA-DIAPH1 signaling pathway plays an important role in ERBB2-dependent stabilization of microtubules at the cell cortex. It controls the localization of APC and CLASP2 to the cell membrane, via the regulation of GSK3B activity. In turn, membrane-bound APC allows the localization of the MACF1 to the cell membrane, which is required for microtubule capture and stabilization. Plays a role in the regulation of cell morphology and cytoskeletal organization. Required in the control of cell shape. Plays a role in brain development. Also acts as an actin nucleation and elongation factor in the nucleus by promoting nuclear actin polymerization inside the nucleus to drive serum-dependent SRF-MRTFA activity (By similarity).
Synonyms: DRF1; hDIA1; LFHL1; mDia1; DFNA1; DIA1; SCBMS
Tractability: Antibody: its Gene Ontology location is reachable by antibodies, with high confidence; UniProt places it where antibodies can reach, with medium confidence. PROTAC: ubiquitination databases record sites on it; its protein half-life has been measured.
Gene: Protein-coding gene on chromosome 5 (141,515,016 to 141,619,055, reverse strand). Ensembl gene ENSG00000131504.
Subcellular location: Cell membrane; Cell projection, ruffle membrane; Cytoplasm, cytoskeleton; Cytoplasm, cytoskeleton, microtubule organizing center, centrosome; Cytoplasm, cytoskeleton, spindle; Cytoplasm; Nucleus
Subcellular location (Human Protein Atlas): Cytosol; Plasma membrane
Pathways (Reactome):
Signal Transduction: ERBB2 Regulates Cell Motility; RHO GTPases Activate Formins; RHOA GTPase cycle; RHOB GTPase cycle; RHOC GTPase cycle; RHOD GTPase cycle; RHOF GTPase cycle
Developmental Biology: Regulation of MITF-M dependent genes involved in invasion
Immune System: Neutrophil degranulation
Gene Ontology:
Molecular function: protein binding; RNA binding; transmembrane transporter binding; signaling receptor binding; actin binding; identical protein binding; profilin binding; small GTPase binding
Biological process: cellular response to histamine; protein localization to microtubule; regulation of cytoskeleton organization; regulation of microtubule-based process; regulation of release of sequestered calcium ion into cytosol; actin cytoskeleton organization; actin filament polymerization; cytoskeleton organization; sensory perception of sound; brain development; neuron projection development; synaptic vesicle endocytosis
Cellular component: mitotic spindle; actin filament; cytoplasm; cytosol; ficolin-1-rich granule membrane; nucleus; plasma membrane; secretory granule membrane; brush border; centrosome; cytoskeleton; neuron projection; presynapse; ruffle membrane; spindle
Genetic constraint (gnomAD): Loss-of-function variants: 34 observed, 123.25 expected, observed/expected ratio (o/e) 0.28, 90% interval 0.21 to 0.37. The upper end of that interval is the gene's LOEUF score, 0.37, which puts it in group 1 of 6, group 1 being the genes least tolerant of losing a copy. Missense variants: 1,258 observed, 1,519 expected, observed/expected ratio (o/e) 0.83, 90% interval 0.79 to 0.87. Synonymous variants: 543 observed, 536.29 expected, observed/expected ratio (o/e) 1.01, 90% interval 0.94 to 1.09.
Gene-disease validity (ClinGen):
ClinGen rates the evidence that DIAPH1 causes each of these diseases.
DIAPH1-related sensorineural hearing loss-thrombocytopenia syndrome (autosomal dominant): Definitive.
progressive microcephaly-seizures-cortical blindness-developmental delay syndrome (autosomal recessive): Definitive.
Homologues: Orthologues: chimpanzee DIAPH1 (98% identical), macaque DIAPH1 (94% identical), dog DIAPH1 (90% identical), mouse Diaph1 (90% identical), rat Diaph1 (90% identical), pig DIAPH1 (88% identical), guinea pig DIAPH1 (87% identical), tropical clawed frog DIAPH1 (64% identical), Caenorhabditis elegans daam-1 (19% identical), Drosophila melanogaster Frl (17% identical), Caenorhabditis elegans frl-1 (16% identical), Caenorhabditis elegans fhod-1 (11% identical), and 2 more. Paralogues in human: DIAPH2 (48% identical), DIAPH3 (44% identical), DAAM1 (20% identical), INF2 (20% identical), DAAM2 (19% identical), FMNL2 (19% identical), FMN2 (18% identical), FMNL3 (18% identical), FMNL1 (18% identical), FHOD3 (15% identical), GRID2IP (14% identical), FHOD1 (13% identical), and 6 more.
Diseases named in the same sentence as DIAPH1 in open-access papers:
DIAPH1 is named in the same sentence as 125 diseases in open-access papers, as found by Europe PMC text mining. Sharing a sentence is not in itself a finding about the gene and the disease. The quoted sentences say what the papers report.
hearing loss (17 papers, 2012 to 2025). "Investigates DIAPH1 gene mutations in patients with sensorineural hearing loss, enriching biological knowledge and enabling more personalized predictive models." (PMID 41007453, 2025). "A pathogenic variant in the DIAPH1 gene was identified in a Japanese family with progressive hearing loss and macrothrombocytopenia." (PMID 39578953, 2024). "Mutations in two formin-related hearing loss genes, DIAPH1 and DIAPH3, are predicted to result in a gain-of-function mechanism." (PMID 38498576, 2024). "Since the identification of a mutation in DIAPH1 as the cause of sensorineural hearing loss in a large Costa Rican family, more families with a dominant pedigree caused by DIAPH1 mutation have been described elsewhere in the world." (PMID 34685534, 2021). "This type of hearing loss is uncommon and has been associated with only the DIAPH1, MYO7A and WFS1 genes." (PMID 22938506, 2012). "Interestingly, a gain-of-function variant in DIAPH1 gene, responsible for macrothrombocytopenia and hearing loss, increases actin polymerization and stabilizes microtubules." (PMID 28058271, 2016). "We recently showed, through an application of our similarity regression approach, that the introduction of a premature stop codon present in two unrelated individuals in the BPD project truncates DIAPH1’s 3′ auto-inhibitory domain and causes macrothrombocytopenia, hearing loss, and mild bleeding." (PMID 26924528, 2016). "Interestingly, we identified the missense mutation, p.P678S of DIAPH1 in this family, and it showed coincident audiographical configuration with known DFNA1 (DIAPH1) hearing loss." (PMID 22938506, 2012). "In humans, defects in two of the three diaphanous genes (DIAPH1 and DIAPH3) have been associated with different types of hearing loss." (PMID 36689403, 2023). "The remaining gene variants in CEACAM16, COL11A1, COL9A2, DIAPH1, TCOF1 were tested for segregation with the hearing loss phenotype in the extended family." (PMID 35292975, 2022). "Mutations in DIAPH1 and DIAPH3 have been associated with different types of hearing loss." (PMID 35681420, 2022). "In humans, defects in DIAPH1 and DIAPH3 have been associated with different types of hearing loss." (PMID 35681420, 2022).
diabetes (13 papers, 2017 to 2025). "In the sections to follow, this review considers the evidence linking RAGE and DIAPH1 to well-known complications of diabetes—that is, atherosclerosis and diabetes-associated kidney diseases (DKD)—and presents the results of recent studies." (PMID 35562970, 2022). "This Review presents current knowledge regarding the roles for RAGE and DIAPH1 in the causes and consequences of diabetes, from obesity to CVD." (PMID 32211423, 2020). "Furthermore, although we observed partial rescue in the morphology of SCN in diabetes with loss of Diaph1, this rescue was limited to diameters of nerve fibers and axons." (PMID 41148850, 2025). "Indeed, studies in mDia1 KO diabetic mice suggest a role of DIAPH1 in the pathogenesis of diabetes-associated nephropathy." (PMID 34685534, 2021). "The cross-talk between RAGE and Diaph1 in the neurological complications of diabetes and cancer should be the subject of further research." (PMID 39335163, 2024). "At six months of diabetes the amount of Diaph1 as well as PFN1 was decreased and the relative amount of CML-AGE was elevated when compared to control mice (P ≤ 0.01, P ≤ 0.01, P ≤ 0.05, respectively)." (PMID 37462767, 2023). "In the sections to follow, the role of RAGE/DIAPH1 in a key microvascular complication of diabetes—that is, in diabetic kidney disease (DKD)—is considered." (PMID 35562970, 2022). "Validation of the specificity of our results is needed, likely via the evaluation of DIAPH1 changes in a series of female reproductive disorders and diabetes or obesity patients." (PMID 35185386, 2022). "In the broader context, the published evidence supports roles for RAGE/DIAPH1 in distinct complications of diabetes; these areas will be considered in the section to follow." (PMID 35562970, 2022). "Herein, we demonstrate that, at the systemic level, CRISPR deletion of Diaph1 fails to ameliorate diabetes-induced weight loss in mice." (PMID 41148850, 2025). "Surprisingly, loss of Diaph1 is not enough to reverse the reduction in β-actin levels in nerve fibers induced by diabetes." (PMID 41148850, 2025). "It has been suggested that DIAPH1 could have a role in diabetes and obesity through its interaction with RAGE." (PMID 34685534, 2021). "Our previous studies indicated that proteins involved in actin cytoskeleton dynamics, Diaph1, PFN1 and ACTB, were down-regulated in the sciatic nerve of wild-type mice during long-term diabetes." (PMID 41303665, 2025). "Several studies have emphasized the role of DIAPH1 in RAGE signal transduction, which is related to diabetes and obesity." (PMID 35185386, 2022). "Moreover, we observed the elevated levels of MNCV in T1D mice with global deletion of Diaph1 and AGER genes vs. WT mice at six months of diabetes (p ≤ 0.0001)." (PMID 41303665, 2025). "We assumed, then, that global deletion of Diaph1 does not affect actin cytoskeleton dynamics in the sciatic nerve during diabetes." (PMID 41148850, 2025).
Macrothrombocytopenia (13 papers, 2016 to 2025). "DIAPH1 promotes the formation of platelets in megakaryocytes through the regulation of actin and the microtubule cytoskeleton, which can cause macrothrombocytopenia and extend the spectrum of DIAPH1‐related diseases." (PMID 39822761, 2025). "Variants associated with DIAPH1-related macrothrombocytopenia result in the constant activation of the DIAPH1 protein, leading to disruption of cytoskeletal and microtubule function, thereby impairing proplatelet formation." (PMID 38915998, 2024). "In 2016, researchers from the University of Bristol confirmed that the gain-of-function variant DIAPH1 caused macrothrombocytopenia and hearing loss." (PMID 34912812, 2021). "Our finding that variants in DIAPH1 can cause macrothrombocytopenia is an example of how this up-weighting can improve the inference." (PMID 26924528, 2016). "Interestingly, a heterozygous premature truncation of DIAPH1 was first reported to cause fully-penetrant autosomal dominant sensorineural deafness and macrothrombocytopenia (also called DFNA1) in a large Costa Rican kindred." (PMID 39076976, 2024). "This suggests that the disease states characterized by gain of function, such as autosomal dominant hearing loss and macrothrombocytopenia, may arise from enhanced actin assembly mediated by DIAPH1 dysregulation." (PMID 37832872, 2023). "Indeed, a gain of function variant of formin mDia1 (DIAPH1) is linked to macrothrombocytopenia in humans." (PMID 32981398, 2021). "Mutations in DIAPH1, including those in the basic “RRKR” motif of its autoregulatory domain, diaphanous autoinhibitory domain (DAD), are implicated in hearing loss, macrothrombocytopenia, and cardiovascular diseases." (PMID 37832872, 2023). "Dominant gain-of-function DIAPH1 variants cause sensorineural deafness and macrothrombocytopenia (DFNA1), while homozygous DIAPH1 loss leads to seizures, cortical blindness, and microcephaly syndrome (SCBMS)." (PMID 36212620, 2022). "There are a series of DIAPH1-related diseases due to DIAPH1 variants or deficiency, such as microcephaly syndrome (SCBMS), immunodeficiency, mitochondrial dysfunction, macrothrombocytopenia, and hearing loss." (PMID 35185386, 2022). "In humans, dominant gain-of-function DIAPH1 variants cause sensorineural deafness and macrothrombocytopenia (DFNA1), while homozygous DIAPH1 loss leads to seizures, cortical blindness, and microcephaly syndrome (SCBMS)." (PMID 36212620, 2022). "Patients with rare causative variants in DIAPH1 have moderate macrothrombocytopenia without bleeding complications, but often mild neutropenia and severe sensorineural deafness can also be observed." (PMID 38915998, 2024). "Dominant gain-of-function DIAPH1 variants cause macrothrombocytopenia and sensorineural deafness (autosomal dominant non-syndromic hearing loss 1 (DFNA1)), while homozygous loss of DIAPH1 results in seizures, cortical blindness, and microcephaly syndrome (SCBMS)." (PMID 38915998, 2024).
Thrombocytopenia (13 papers, 2021 to 2026). A reduction in the number of circulating thrombocytes. "Monoallelic mutations in DIAPH1, a gene implicated in proplatelet expansion and cytoskeleton assembly, cause abnormally big platelets in DIAPH1-related thrombocytopenia." (PMID 41167018, 2025). "Pathogenic variants of the DIAPH1 gene are involved in a number of diseases: heterozygous gain-of-function variants cause deafness and thrombocytopenia (OMIM 124900) and have also been associated with sporadic moyamoya disease." (PMID 36212620, 2022). "It is of note that a moderate increase in the expression of DIAPH1 could be responsible for the thrombocytopenia associated with diseases caused by mutation in other genes, as may be the case for Roifman syndrome." (PMID 34685534, 2021). "Frequent thrombophilia-related variants occurred in F5, SERPINC1, MTHFR, and FII, and inherited thrombocytopenias were linked to MPL, ANKRD26, THPO, DIAPH1, and ADAMTS13." (PMID 41929524, 2026). "Long after the discovery of the DIAPH1 mutation as the cause of DFNA1, affected individuals were found to present asymptomatic thrombocytopenia and, sometimes, asymptomatic mild neutropenia, which consists of abnormally low levels of neutrophils in the blood." (PMID 34685534, 2021). "This drug can enable DIAPH1-related thrombocytopenia to be temporarily corrected prior to surgery, thereby obviating platelet transfusion." (PMID 33926054, 2021). "DIAPH1-related thrombocytopenia is an autosomal dominant defect with macrothrombocytopenia and variable neutropenia, as well as hearing loss beginning in the first decade of life (at much younger ages than in MYH9-RD)." (PMID 33926054, 2021). "Since identifying DIAPH1 as the first causative gene of ADNSHL in a large Costa Rican family in 1997, among the reported ones, only a few mutations in this gene have been reported with DFNA1 without thrombocytopenia, and most of them have additional symptoms (DFNA1 + Thrombocytopenia)." (PMID 37543941, 2023). "In particular, heterozygous mutations in DIAPH1 are responsible for autosomal dominant deafness with or without thrombocytopenia (DFNA1, MIM #124900), whereas regulatory mutations inducing the overexpression of DIAPH3 cause autosomal dominant auditory neuropathy 1 (AUNA1, MIM #609129)." (PMID 35681420, 2022). "The patient’s symptoms cannot be explained only by the phenotype terms of DIAPH1 (deafness, autosomal dominant 1, with or without thrombocytopenia, OMIM #124900, seizures, cortical blindness, microcephaly syndrome, OMIM #616632)." (PMID 39202364, 2024). "Heterozygous and likely gain-of-function mutations in the DIAPH1 gene, located on chromosome 5, are associated with autosomal dominant deafness 1 with or without thrombocytopenia (DFNA1, MIM #124900)." (PMID 35681420, 2022).
deafness (12 papers, 2016 to 2024). An inherited or acquired condition characterized by the complete loss of the ability to hear from one or both ears. "Autosomal dominant nonsyndromic sensorineural hearing loss, DFNA1, which is characterized by progressive deafness starting in childhood, is caused from the c.3634+1G>T mutation in DIAPH1 (p.Ala1212ValfsX22)." (PMID 27707755, 2016). "Mutations in DIAPH1 produce deafness, autosomal dominant 1 (DFNA1, MIM: 124900)." (PMID 34685534, 2021). "The c.3634+1G>T DIAPH1 mutation causes autosomal dominant nonsyndromic sensorineural hearing loss, DFNA1, characterized by progressive deafness starting in childhood." (PMID 27707755, 2016). "Autosomal dominant mutations of DIAPH1, (possibly resulting in gain of function), were associated with deafness with or without thrombocytopenia." (PMID 39120629, 2024). "Autosomal dominant mutations of DIAPH1, which are believed to be gain of function mutations, are associated with deafness with or without cytopenia (DFNA1)." (PMID 39120629, 2024). "Importantly, pathogenic variants in DIAPH1 and DIAPH3 have been shown to cause deafness." (PMID 36400760, 2022). "Interestingly, of 118 deafness genes, several genes have been reported to be associated with auditory neuropathy, a hearing dysfunction characterized by impaired transmission of signal to the auditory nerve by the presynaptic inner hair cells, such as PJVK, NARS2, SLC17A8, DIAPH3 and DIAPH1." (PMID 37062025, 2023).